IL2 (interleukin 2)
Diseases named in the same sentence as IL2 in open-access papers (continued):
Sharing a sentence is not in itself a finding about the gene and the disease.
Right ventricular hypertrophy (1 paper, 2021). In this case the right ventricle is more muscular than normal, causing a characteristic boot-shaped (coeur-en-sabot) appearance as seen on anterior- posterior chest x-rays. "Besides, in mice with existing left ventricular failure, administration of IL-2 (also named as T-cell growth factor) significantly increased Tregs in the lung, consecutively reduced pulmonary macrophages and CD8+ T cell infiltration, and attenuated right ventricular hypertrophy." (PMID 34276413, 2021).
seborrheic dermatitis (1 paper, 2026). A chronic, inflammatory skin disorder that affects the scalp, central face and skin folds; it is characterized by scaling and itching. "The authors concluded that seborrheic dermatitis could be due to the overexpression of IL-10, which downregulated the production of IL-2 and IFN-γ and promoted the synthesis of IgA and IgG." (PMID 41602867, 2026).
Senile plaques (1 paper, 2014). Senile plaques are extracellular deposits of amyloid in the gray matter of the brain. "IL1A, IL1B, IL2, IL8, IFNγ, and TNFα have been found to be associated with senile plaques." (PMID 25197660, 2014).
sensitization (1 paper, 2015). "Skin sensitization is primary associated with induction of Th1 cells, promoting a cytotoxic CD8+ T-cell response and secretion of IL-2 and interferon (IFN)-γ, while respiratory sensitization generally involve CD4+ Th2 cells and are characterized by high levels of IL-4, IL-10 and IL-13." (PMID 25760038, 2015).
septic shock (1 paper, 2015). Shock caused by infection; frequently caused by gram negative bacteria, although some cases have been caused by other bacteria, viruses, fungi, and protozoa; characterized by fever, chills, tachycardia, tachypnea, and hypotension. "Interleukin-2 (IL-2), which is occasionally used in oncological therapy, induces a pathological increase in capillary permeability, manifested by hypotension, tachycardia, and oliguria often seen in septic shock." (PMID 26136776, 2015).
shigellosis (1 paper, 2017). Shigellosis is a bacterial infection leading to dysentery and is caused by Shigella, which are small, ubiquitous Gram-negative bacteria belonging to the enterobacteria family. "The p-values were significant (<0.05) for IL-1β, IL-10, IFN-γ and TNF-α, but IL-2 and IL-4 levels were insignificant in shigellosis patients’ sera." (PMID 28767653, 2017).
silicosis (1 paper, 2010). Silicosis is a respiratory disease caused by breathing in (inhaling) silica dust. "In silica-treated group, the level of IL-2 increased clearly at the early inflammatory stage of silicosis (day 7) and decreased during the fibrotic reaction of silicosis (day 28 and 56)." (PMID 21072213, 2010).
skin reaction (1 paper, 2012). "Furthermore, NVP-induced skin reactions were prevented by use of the immunosuppressant drug cyclosporine, a known inhibitor of Il-2 production." (PMID 22957276, 2012).
skin toxicity (1 paper, 2014). "Skin toxicity (p < 0.001; HR = 0.29; CI 95% = 0.16–0.54) and use of IL-2 (p < 0.001; HR = 0.33; CI 95% = 0.18–0.60) were independently associated with improvement of survival." (PMID 25271833, 2014).
smallpox (1 paper, 2024). A condition that is caused by infection with Variola, and that is characterized by small, raised bumps. "The current data indicate that two-thirds of HIV-positive patients can produce IFN-γ and IL-2 secreting orthopoxvirus-specific T cells after two vaccinations against smallpox and all after mpox infection." (PMID 38400115, 2024).
spinal injury (1 paper, 2021). A injury that involves the vertebral column. "The levels of cytokines CXCL5, CCL11, CXCL11, IL10, TNFα, and MIF were different between patients with baseline American Spinal Injury Association Impairment Scale (AIS) grades of A or B, whilst IL2 (>2 fold) and MIP-3a (>6 fold) were significantly expressed in the cervical and thoracic regions." (PMID 33806460, 2021).
splenic marginal zone lymphoma (1 paper, 2017). Splenic marginal zone lymphoma is a rare, indolent B-cell non-Hodgkin lymphoma characterized by abnormal clonal proliferation of mature B-lymphocytes with involvement in the spleen, bone marrow and, frequently, the blood. "All the 3 evaluable patients with advanced, progressive B-NHL (2 FL, 1 splenic marginal zone lymphoma (SMZL)) who received conditioning chemotherapy followed by an infusion of anti-CD19 28ζ CAR-T cells and a course of IL-2 obtained PR." (PMID 28466386, 2017).
staphylococcal food poisoning (1 paper, 2010). "The enteric effects of SEs likely resulted from IL-2 release from activated T cells as IL-2 given to cancer patients produces side effects similar to staphylococcal food poisoning." (PMID 22069668, 2010).
staphylococcus aureus infection (1 paper, 2025). An infectious process in which the bacteria Staphylococcus aureus is present. "Moreover, AP-1 directly regulates the transcription of inflammatory mediators (TNF-α, IL-2, IL-12, IL-1β, IL-8) and their receptors (IL-2R) in the cytokine–cytokine receptor interaction and Staphylococcus aureus infection pathways." (PMID 40647090, 2025).
Strongyloides infection (1 paper, 2021). "A diminution in mycobacterial-specific Th1 cells and Th17 cells and their relevant cytokines (i.e., IFN-γ, TNF-α and IL-2, IL-17A, and IL-17F) has been found in patients with concomitant filarial or Strongyloides infection." (PMID 34202662, 2021).
Systemic capillary leak syndrome (1 paper, 2015). Systemic capillary leak syndrome (SCLS) is a severe systemic disease due to increased capillary permeability, characterized by episodes of hypotension, edema and hypovolemia. "IL-2 treatment-related toxicities, including systemic capillary leak syndrome, a cascade of plasma extravasation and vascular collapse, limit its delivery in clinical practice." (PMID 25815245, 2015).
T-cell chronic lymphocytic leukemia (1 paper, 2017). "The interleukin-2 dependent Kit225 cell line was established from a patient diagnosed with T-cell chronic lymphocytic leukemia." (PMID 29029444, 2017).
Takotsubo syndrome (1 paper, 2021). "However, the elevated IL-2 and IL-4 levels in Takotsubo syndrome point towards activation of circulating CD4 and CD8 T cells as these are the primary source of these interleukins." (PMID 34095448, 2021). "IL-2, IL-4, IL-10, IFN-γ and TNF-α at admission were shown to be significantly higher in patients with acute Takotsubo syndrome compared to patients with AMI, conversely, IL-6 was much higher in AMI patients." (PMID 34095448, 2021).
temporal lobe epilepsy (1 paper, 2024). A localization-related (focal) form of epilepsy characterized by recurrent seizures that arise from foci within the temporal lobe, most commonly from its mesial aspect. "As a factor that plays an important immune role, elevated levels of IL-2 over-activate signaling pathways, leading to a worse prognosis in temporal lobe epilepsy." (PMID 38855442, 2024).
Testicular torsion (1 paper, 2014). Testicular torsion is when the spermatic cord to a testicle twists, cutting off the blood supply. "Compared to the sham group, the levels of proinflammatory cytokines (IL-2 and TNF-α) and MDA were significantly increased in testes after testicular torsion, while the levels of SOD and GPx were decreased (resp., P < 0.05)." (PMID 24904198, 2014).
thrombotic microangiopathy (1 paper, 2023). The syndromes of microangiopathic hemolytic anemia, thrombocytopenia, and variable signs of organ impairment, due to platelet aggregation in the microcirculation. "Cyclosporine, an immunomodulating drug that inhibits T-cell activation and interleukin-2 production, has successfully treated refractory TTP; however, its use is rare now because it can also cause thrombotic microangiopathy, independent of TTP." (PMID 38234934, 2023).
Tinnitus (1 paper, 2021). Tinnitus is an auditory perception that can be described as the experience of sound, in the ear or in the head, in the absence of external acoustic stimulation. "In addition, when CBT was administered to patients with tinnitus, the level of IL-2, which is known to be involved in cellular immunity, was increased compared to that in patients who received only sound therapy." (PMID 34205595, 2021). "In a study of tinnitus with presbycusis, TGF-β was low in the elderly, and IL-1α was high in patients with tonal tinnitus, and IL-2, representing cellular immunity, was low in patients with partial or complete residual inhibition." (PMID 34205595, 2021).
tonsillitis (1 paper, 2020). Inflammation of the tonsillar tissue. "Levels of IL-1β, IL-2 and IL-6 showed a significant increase in the recurrent tonsillitis group when compared to the hypertrophy group." (PMID 30213594, 2020).
toxicity (1 paper, 2020). The degree to which an agent can damage an organism. "The trend for an association between increased concentrations of IL-2 and higher grade of acute genitourinary toxicity (b = 0.018; p = 0.081) was observed." (PMID 33149212, 2020).
transverse myelitis (1 paper, 2022). "There was no case of transverse myelitis in this study, which might be explained by the absence of concomitant IL-2 therapy." (PMID 35454826, 2022).
trigeminal neuralgia (1 paper, 2023). Trigeminal neuralgia is a nerve disorder that causes a stabbing or electric-shock-like pain in parts of the face. "This is the first study to explore the causal association between IL2 levels and trigeminal neuralgia risk by a two-sample MR analysis based on a large amount of GWAS data of IL2 (exposure) and trigeminal neuralgia (outcome)." (PMID 37123369, 2023). "Using the IVW method, we found that IL2 was associated with the risk of trigeminal neuralgia with an OR of 1.203 (95% CI = 1.004–1.443, p = 0.045)." (PMID 37123369, 2023). "In inverse variance weighting, we found that IL2 was associated with the risk of trigeminal neuralgia with an OR of 1.203 (95% CI = 1.004–1.443, p = 0.045)." (PMID 37123369, 2023). "We assessed the causal association between IL2 levels and trigeminal neuralgia." (PMID 37123369, 2023). "Finally, IL2 was selected and we observed that IL2 was causally associated with immune cell infiltrates in trigeminal neuralgia." (PMID 37123369, 2023). "This MR study showed that serum IL2 levels might be causally associated with an increased risk of trigeminal neuralgia." (PMID 37123369, 2023). "This also indicates that there was no dominant SNP in IL2 levels and trigeminal neuralgia, and the previous MR results were valid." (PMID 37123369, 2023). "To ensure that SNPs are not related to any confounding factors between IL2 and trigeminal neuralgia, we chose only participants from European populations." (PMID 37123369, 2023).
type 2 thrombocytopenia (1 paper, 2013). "In several cell lines, PaCS development follows cell differentiation/activation by trophic factors and cytokines, such as GM-CSF and IL-4 for DCs, IL-2 and IL-15 for NK cells, or thrombopoietin, IL-6 and IL-11 for megakaryocytes in type 2 thrombocytopenia." (PMID 24358206, 2013).
type-2 diabetic nephropathy (1 paper, 2019). "Short Description: A novel bifunctional cytokine IL233, bearing IL-2 and IL-33 activities reverses inflammation and protects from type-2 diabetic nephropathy through promoting T-regulatory cells and type 2 immune response." (PMID 31191312, 2019).
typhoid fever (1 paper, 2025). A bacterial infectious disorder contracted by consumption of food or drink contaminated with Salmonella typhi. "In the typhoid fever group, IL-2 was equally strongly and positively correlated to IL-6 (r = −0.464, p = 0.01)." (PMID 40014608, 2025).
uremia (1 paper, 2019). A clinical syndrome associated with the retention of renal waste products or uremic toxins in the blood. "Those who are continuously undergoing high throughput blood purification have decreased serum levels of CRP, interleukin-2, and tumor necrosis factor-α, and high throughput hemodialysis may be beneficial for the prevention of infections in patients with uremia." (PMID 30818331, 2019).
urolithiasis (1 paper, 2024). Stone(s) within the urinary tract. "Urolithiasis also impacts the expression of cytokines such as IL-2, CTACK, IL-5, IL-7, IL-8, GRO-α, MIG, and MIP-1α." (PMID 39021826, 2024).
urothelial carcinoma (1 paper, 2025). A malignant neoplasm derived from the transitional epithelium of the urinary tract (urinary bladder, ureter, urethra, or renal pelvis). "A recent review compiling data on the combined treatment of IL-2 and anti-PD-1 showed positive potential for application in urothelial carcinoma, but more research is still needed." (PMID 40699676, 2025). "Additionally, IL-2 complexes (IL-2cs) were found to reduce tumor size in mouse orthotopic urothelial carcinoma (UC) cell line MB49 and mouse bladder transitional cell carcinoma cell line MBT-2." (PMID 40699676, 2025).
urothelial cell carcinoma (1 paper, 2020). "The effectiveness of IL-2 application for urothelial cell carcinoma, that is, NMIBC, has been proven on various occasions." (PMID 33027905, 2020).
uterine fibroids (1 paper, 2025). "In line with this, in uterine fibroids, the phagocytic ability of neutrophils is affected by the serum levels of IL-2, IL-17A, IL-6, and IL-4." (PMID 40943781, 2025).
varicocele (1 paper, 2021). A condition characterized by the dilated tortuous veins of the spermatic cord with a marked left-sided predominance. "To evaluate the effect of lycopene on inflammation after varicocele in testis, we detected IL-1β and IL-2 by ELISA." (PMID 34055003, 2021). "Lycopene improved the hypoxia-induced testicular injury by inhibiting the expression of PROK2 and decreasing levels of IL-1β and IL-2, which might show us a novel and promising treatment for varicocele testicular injury." (PMID 34055003, 2021).
ventricular extrasystoles (1 paper, 1992). "Despite normal cardiac tests prior to inclusion into the study, abnormalities of the cardiac rhythm ranging from tachycardia to ventricular extrasystoles occurred in 44% of the patients and IL2 cardiac toxicity was responsible for one toxic death." (PMID 1586600, 1992).
ventricular tachycardia (1 paper, 2014). A disorder characterized by an electrocardiographic finding of three or more consecutive complexes of ventricular origin with a rate greater than a certain threshold (100 or 120 beats per minute are commonly used). "Ventricular tachycardia requires evaluation for cardiac damage and is an absolute contraindication to more IL-2." (PMID 31546315, 2014). "Ventricular tachycardia or evidence of ischemic myocardial damage are indications for permanently stopping IL-2 treatment." (PMID 31546315, 2014).
viral pneumonia (1 paper, 2025). Inflammation of the lung parenchyma that is caused by a viral infection. "In patients with viral pneumonia, positive correlations were found between TNF-α and Fusobacterium nucleatum (p = 0.005), while IL-2 positively correlated with Capnocytophaga granulosa (p = 0.011)." (PMID 41011430, 2025).
tumor (4,369 papers, 1983 to 2026). "The linked IL2 molecules provide a milieu of increased IL2 concentration and function to chemoattract immune cells, e.g., T cells and NK cells to the tumor microenvironment." (PMID 40828812, 2025). "In the present study, we developed a novel cancer immunotherapy approach by using an oncolytic VACV co-expressing IL2 with tumor-associated antigen epitopes for the activation and amplification of cytotoxic CD8+ T and CD4+ T cells in mice." (PMID 41050655, 2025). "After overexpression of MINDY1, Perforin and IL-2 protein levels in tumor tissues were decreased significantly, and silencing PD-L1 caused a rise in Perforin and IL-2." (PMID 41179305, 2025). "A further significant challenge linked to IL-2 immunotherapy involves the stimulation of the regulatory T (Treg) cells, which promote suppression of the anti-tumor immune responses." (PMID 41150778, 2025). "This treatment regimen avoided the systemic IL-2-related therapeutic deficiencies while generating beneficial anti-tumor immunity in glioblastoma multiforme." (PMID 40821119, 2025). "Future studies are required to evaluate the systemic and local effects of HIF-PH inhibitors and IL-2 induction on tumor-associated immune cells, including macrophages and fibroblasts." (PMID 40343532, 2025). "Modified IL-2 variants such as fusion proteins or antibody conjugates targeting CD122 have already demonstrated anti-tumor responses in preclinical models." (PMID 40502703, 2025). "By fusing IL-2 with antibodies targeting tumor-associated antigens, researchers aimed to localize cytokine activity to the TME, employing diverse targeting strategies and modulating pharmacokinetic properties with different antibody formats." (PMID 39852848, 2025). "These vaccines deliver genetic material—either plasmid DNA or messenger RNA (mRNA)—encoding specific tumor antigens, sometimes alongside immunostimulatory molecules such as cytokines (e.g., IL-2, IL-12, GM-CSF), to promote robust and durable immune activation." (PMID 40725830, 2025). "The solution of this issue lies in targeting the tumor with IL-2 in association with an anti-tumor-specific antibody generating an immunocytokine." (PMID 39852848, 2025). "More recently, Nemvaleukin Alfa, a reformulated IL-2 variant, was developed to retain the anti-tumor benefits of IL-2 while minimizing the cytokine-induced toxicity associated with earlier IL-2 therapies." (PMID 40004731, 2025). "TG4010 is a recombinant modified bovine pox virus suspension capable of encoding MUC1 tumor related antibodies and interleukin-2 (IL-2)." (PMID 39179939, 2025). "These challenges underscore the importance of integrating IL-2 variants with immune checkpoint inhibitors or metabolic modulators to achieve sustained tumor control." (PMID 41394821, 2025). "In one study, tumor-bearing mice were injected intraperitoneally with plasmids encoding an IL-2/anti-PD-1 fusion protein." (PMID 40699676, 2025). "Variants of IL2 are successfully used in the clinical setting to boost NK cell infiltration and anti‐tumor immunity." (PMID 40397803, 2025). "Current approaches involve engineered IL-2 variants combined with immune checkpoint inhibitors (ICIs), mAbs, or adoptive T cell therapies to boost anti-tumor immunity." (PMID 40868199, 2025). "The expression of the trimeric IL-2 receptor complex (IL-2Rαβγ) underlies the high-affinity binding of IL-2 to these tumor-protecting immune cells." (PMID 41150778, 2025). "This suggests that whereas IL-2 and tumor-associated peptides produced by VACV can activate CD8+ T cells via cytokine support and TCR interaction, they cannot rescue the exhausted T cells." (PMID 41050655, 2025). "Accelerated tumor growth in the Gsdmdfl/fl CD4cre mice was associated with decreased cytokine levels, including IL-2, IL-12, IL-4, and IL-10." (PMID 40759573, 2025).